TMEM187 (transmembrane protein 187)
Synonyms: CXorf12; DXS9878E; ITBA1
Tractability: Antibody: UniProt predicts a signal peptide or a membrane-spanning region.
Gene: Protein-coding gene on chromosome X (153,972,754 to 153,983,194, forward strand). Ensembl gene ENSG00000177854.
Subcellular location: Membrane
Subcellular location (Human Protein Atlas): Cytosol; Nucleoli
Gene Ontology:
Molecular function: protein binding
Cellular component: transport vesicle; membrane
Homologues: Orthologues: chimpanzee TMEM187 (99% identical), macaque TMEM187 (94% identical), dog TMEM187 (74% identical), rabbit TMEM187 (68% identical), tropical clawed frog tmem187 (52% identical), zebrafish tmem187 (51% identical).
Diseases named in the same sentence as TMEM187 in open-access papers:
TMEM187 is named in the same sentence as 14 diseases in open-access papers, as found by Europe PMC text mining. Sharing a sentence is not in itself a finding about the gene and the disease. The quoted sentences say what the papers report.
autism spectrum disorder (3 papers, 2019 to 2024). A spectrum of developmental disorders that includes autism, and Asperger syndrome. "Our research findings will be discussed related specifically to both the SYTL4 and TMEM187 gene variants seen in our patient and evidence for the two gene variants playing a role in the causation of high-functioning autism spectrum disorder." (PMID 31323913, 2019). "Notably, IGKC, known for its role in immunological and cancer-related processes, along with TMEM187 and SYTL4—genes associated with autism spectrum disorders—show interactions with key genes in these areas." (PMID 38778304, 2024). "We describe a 7-year-old male with high-functioning autism spectrum disorder presenting for genetic services and whole exome sequencing following a normal microarray analysis, and variants were found in two X-linked genes: SYTL4 and TMEM187." (PMID 31323913, 2019). "TMEM187 and SYTL4 genes have been found to interact directly with known autism spectrum disorder genes, with their mRNAs present in extracellular vesicles in the nervous system, facilitating the translation of active proteins in target cells." (PMID 37710308, 2023).
autoimmune disease (2 papers, 2023 to 2024). A disorder resulting from loss of function or tissue destruction of an organ or multiple organs, arising from humoral or cellular immune responses of the individual to their own tissue constituents. "The TMEM187 locus has also been associated with other autoimmune disorders such as SLE or rheumatoid arthritis, supporting the hypothesis of a shared genetic background in autoimmune disorders." (PMID 38072919, 2023).
autism (1 paper, 2019). Persistent deficits in social interaction and communication and interaction as well as a markedly restricted repertoire of activity and interest as well as repetitive patterns of behavior. "Research findings will be discussed that relate specifically to SYTL4 and TMEM187 gene variants seen in our patient and as emerging candidate genes for autism." (PMID 31323913, 2019). "TMEM187 is an emerging candidate gene for autism with a discussion undertaken on protein interactome networks, expression profiling and microRNA interaction studies." (PMID 31323913, 2019).
schizophrenia (1 paper, 2019). A major psychotic disorder characterized by abnormalities in the perception or expression of reality. "One of this gene’s related phenotypes is schizophrenia (GWAS catalog for TMEM187 gene: Gene relation via enhancers containing phenotype SNP: Enhancer ID: GH0XJ153980)." (PMID 31323913, 2019).
cancer (2 papers, 2024 to 2025). A tumor composed of atypical neoplastic, often pleomorphic cells that invade other tissues. "The specific role of TMEM187 in cancers has not yet been elucidated, our findings revealed that its mRNA is enriched in tumors, while its higher expression somehow predicted better clinical outcomes." (PMID 39949782, 2025).
tumor (2 papers, 2020 to 2025). "Among them, the expression of TIPRAP, WSCD1, TCP11L2, DPP4, CAB39 and PDPK1 were down-regulated, while PARP1, DEPDC1B, CKAP2, ORMDL2, MRPL44, POLD4 and TMEM187 were increased in tumor group." (PMID 39949782, 2025).
neurodevelopmental disorder (1 paper, 2019). A behavioral and cognitive disorder with onset during the developmental period that involves impaired or aberrant development of intellectual, motor, or social functions.
TMEM187 also shares sentences with these, for which no sentence is quoted: rheumatoid arthritis (2 papers); bipolar disorder (1); celiac disease (1); cervical cancer (1); colorectal adenocarcinoma (1); neurological disorders (1); panic disorder (1).